ADAMTS18 (ADAM metallopeptidase with thrombospondin type 1 motif 18)
Synonyms: ADAMTS21; KNO2; MMCAT
Tractability: Antibody: UniProt places it where antibodies can reach, with medium confidence; UniProt predicts a signal peptide or a membrane-spanning region; its Gene Ontology location is reachable by antibodies, with medium confidence.
Safety:
Unwanted effects reported when the protein is acted on. In parentheses: how it was acted on, where the effect was seen, and who reports it.
hypertension (source: ClinPGx)
Gene: Protein-coding gene on chromosome 16 (77,247,813 to 77,435,034, reverse strand). Ensembl gene ENSG00000140873.
Subcellular location: Secreted, extracellular space, extracellular matrix
Subcellular location (Human Protein Atlas): Midbody; Mitotic spindle; Predicted to be secreted
Pathways (Reactome):
Disease: Defective B3GALTL causes PpS
Extracellular matrix organization: Degradation of the extracellular matrix
Metabolism of proteins: O-glycosylation of TSR domain-containing proteins
Gene Ontology:
Molecular function: metalloendopeptidase activity; metallopeptidase activity
Biological process: eye development; negative regulation of platelet aggregation; extracellular matrix organization; proteolysis
Cellular component: extracellular matrix
Genetic constraint (gnomAD): Loss-of-function variants: 155 observed, 167.81 expected, observed/expected ratio (o/e) 0.92, 90% interval 0.81 to 1.05. The synonymous counts are far from expectation, so gnomAD's model fits this gene poorly and the ratio says little. Missense variants: 2,022 observed, 1,576.9 expected, observed/expected ratio (o/e) 1.28, 90% interval 1.24 to 1.33. Synonymous variants: 780 observed, 591.95 expected, observed/expected ratio (o/e) 1.32, 90% interval 1.24 to 1.4.
Gene-disease validity (ClinGen):
ClinGen rates the evidence that ADAMTS18 causes each of these diseases.
microcornea-myopic chorioretinal atrophy (autosomal recessive): Definitive.
Homologues: Orthologues: chimpanzee ADAMTS18 (99% identical), macaque ADAMTS18 (98% identical), guinea pig ADAMTS18 (91% identical), rabbit ADAMTS18 (90% identical), dog ADAMTS18 (90% identical), pig ADAMTS18 (90% identical), mouse Adamts18 (89% identical), rat Adamts18 (88% identical), tropical clawed frog adamts18 (66% identical), zebrafish adamts18 (65% identical). Paralogues in human: ADAMTS16 (55% identical), ADAMTS6 (36% identical), ADAMTS7 (35% identical), ADAMTS12 (35% identical), ADAMTS10 (33% identical), ADAMTS9 (31% identical), ADAMTS20 (30% identical), ADAMTS2 (29% identical), ADAMTS14 (28% identical), ADAMTS17 (28% identical), ADAMTS19 (28% identical), ADAMTS3 (28% identical), and 13 more.
Diseases named in the same sentence as ADAMTS18 in open-access papers:
ADAMTS18 is named in the same sentence as 58 diseases in open-access papers, as found by Europe PMC text mining. Sharing a sentence is not in itself a finding about the gene and the disease. The quoted sentences say what the papers report.
melanoma (8 papers, 2012 to 2025). A malignant, usually aggressive tumor composed of atypical, neoplastic melanocytes. "Specifically, ADAMTS18 has been implicated in tumorigenesis in melanoma and colorectal cancers, while SLIT1 functions as a tumor suppressor in breast epithelium." (PMID 40868176, 2025). "Mutations in ADAMTS18 play vital roles in promoting cell invasion and metastasis in melanoma, and upregulated ADAMTS18 expression predicts poor survival for patients with STAD." (PMID 35874675, 2022). "Mutated ADAMTS18 also caused reduced adhesion of melanoma cells on laminin-1 and a corresponding increase in cell migration." (PMID 24213506, 2012). "Although ADAMTS18 is a potential tumor suppressor, paradoxically, its mutations seem to have acquired an oncogenic potential in human melanoma." (PMID 24213506, 2012). "The most highly mutated ADAMTS gene in melanoma was identified to be ADAMTS18 with 14 somatic mutations." (PMID 24213506, 2012). "Loss of ADAMTS18 function promotes the growth, migration, and metastasis of melanomas." (PMID 36836780, 2023). "Overexpression of the mutated ADAMTS18 protein in either A375 or Mel-STR melanoma cells (both harbor wild-type ADAMTS18 gene) resulted in higher cell transformation ability while cells overexpressing the wild-type protein behaved similarly with vector-modified cells." (PMID 24213506, 2012). "Mutant ADAMTS18 also promotes migration and invasion of melanoma cells in vitro by reducing adhesion to laminin-I." (PMID 38482210, 2024). "An ADAMTS18 mutant melanoma cell line was established by simulating standard conditions in vivo." (PMID 38482210, 2024). "In addition, mutant melanoma cells reduce their dependence on factors required for cell growth, suggesting a growth-promoting effect of mutant ADAMTS18 on melanoma." (PMID 38482210, 2024). "Moreover, in human melanoma, 19 members belonging to the ADAMTS family were sequenced, with ADAMTS18 having the highest mutation frequency." (PMID 38482210, 2024). "Besides, ADAMTS18, which is also described as potential tumor-suppressor in melanoma, was also strongly downregulated." (PMID 37179302, 2023). "Using shRNA based knockdown, ADAMTS18 was shown to be essential for melanoma cells to migrate." (PMID 24213506, 2012). "In the same study, wild-type ADAMTS18 showed an assay-specific tumor suppressive effect, suppressing melanoma metastasis in vivo but not melanoma cell transformation ability in vitro." (PMID 24213506, 2012).
breast carcinoma (5 papers, 2016 to 2025). "To investigate the association of ADAMTS18 with HER2-positive breast cancer, we developed Her2t/w/Adamts18+/+ and Her2t/w/Adamts18−/− mice with C57BL/6-FVB mixed background for subsequent experiments." (PMID 38287441, 2024). "ADAMTS18 deficiency leads to a significantly increased incidence of mammary tumors and metastasis, as well as mammary hyperplasia in mice, over 30 months of observation." (PMID 38287441, 2024). "In the HER2 transgenic spontaneous mammary tumor mouse model, ADAMTS18 deficiency causes the deposition of mammary ECM molecules, including laminin (LN-511), FN, and type I collagen." (PMID 38482210, 2024). "Several studies have shown an association between ADAMTS18 gene and breast cancer." (PMID 38287441, 2024). "(III) ADAMTS18 expression is silenced or down-regulated in breast cancer cell lines, and demethylation restores ADAMTS18 expression in these cells." (PMID 38287441, 2024). "ADAMTS18 has been identified as an important functional tumor suppressor gene involved in multiple carcinomas, including breast cancer." (PMID 38287441, 2024). "Following previous studies, ADAMTS18 showed tumor suppressive effects by inhibiting epithelial-mesenchymal transition through inhibiting the NF-κB/AKT signaling pathway in breast cancer." (PMID 38482210, 2024). "ADAMTS18 is proposed as an important functional tumor suppressor gene involved in multiple malignancies, including breast cancer." (PMID 38287441, 2024). "ADAMTS18 has been reported to have tumor suppressor activity in esophageal adenocarcinoma, nasopharyngeal carcinoma, colorectal carcinoma, breast carcinoma, lung carcinoma, cervical carcinoma, and clear cell renal cell carcinoma." (PMID 38482210, 2024). "In vivo and in vitro experiments have shown that ADAMTS18 inhibits migration and invasion of breast cancer cells." (PMID 38482210, 2024). "Nevertheless, the incidence of spontaneous mammary tumors was significantly higher in Her2t/w/Adamts18−/− mice than in Her2t/w/Adamts18+/+ mice (31% vs 5.6%, P = 0.01)." (PMID 38287441, 2024). "The mean latency for mammary tumor development was 210 days in Her2t/t mice, 494 days in Her2t/w/Adamts18−/− mice, and 647 days in Her2t/w/Adamts18+/+ mice, respectively." (PMID 38287441, 2024). "This was further supported by the finding that the proliferation, migration and invasion capacity of primary Her2t/w/Adamts18−/− mammary tumor cells were significantly higher than that of primary Her2t/w/Adamts18+/+ mammary tumor cells cultured in vitro." (PMID 38287441, 2024). "The proliferation, migration and invasion capacities of primary Her2t/w/Adamts18−/− mammary tumor cells are significantly higher than those of primary Her2t/w/Adamts18+/+ mammary tumor cells in vitro." (PMID 38287441, 2024). "We demonstrated that Adamts18 gene knockout (Adamts18−/−) resulted in a significantly increased incidence of spontaneous mammary tumors and metastases in heterozygous Her2 transgenic (Her2t/w) mice." (PMID 38287441, 2024). "Scratch would healing assays showed that the migration capacity of Her2t/t and Her2t/w/Adamts18−/− mammary tumor cells was significant increased compared with Her2t/w/Adamts18+/+ mammary tumor cells at 6 h and 12 h, respectively." (PMID 38287441, 2024). "Transwell assays showed that the invasion of Her2t/t and Her2t/w/Adamts18−/− mammary tumor cells was significantly increased compared with Her2t/w/Adamts18+/+ mammary tumor cells at 6 h." (PMID 38287441, 2024). "Among the 10 tumor-bearing Her2t/w/Adamts18−/− mice, 7 developed more than two mammary tumors, while only one mammary tumor was detected in each of the 2 tumor-bearing Her2t/w/Adamts18+/+ mice." (PMID 38287441, 2024). "At 12 h, Her2t/t and Her2t/w/Adamts18−/− mammary tumor cells showed significantly increased proliferation when compared with Her2t/w/Adamts18+/+ mammary tumor cells." (PMID 38287441, 2024).
breast carcinoma (continued). "Here, we evaluated the expression and methylation status of ADAMTS18 in breast cancer cell lines and primary tumors, and further assessed its biological functions." (PMID 28503860, 2017). "We found that ADAMTS18 promoter methylation was observed in 34 out of 48 (70.8%) primary breast carcinoma sample." (PMID 28503860, 2017). "Here, we found promoter methylation and downregulation of ADAMTS18 in primary breast cancer tissues and cell lines." (PMID 28503860, 2017). "In summary, we demonstrate that ADAMTS18 silencing in breast cancer is significantly correlated with promoter CpG methylation." (PMID 28503860, 2017). "In this study, we found frequent downregulation or silencing of ADAMTS18 by promoter methylation in breast cancer cells and primary tissues." (PMID 28503860, 2017). "Results showed that ADAMTS18 was obviously decreased (31/35 of the samples) in breast cancer tissues, as compared with surgical‐margin tissues (P < 0.05)." (PMID 28503860, 2017). "We first evaluated ADAMTS18 expression in a panel of breast cancer cell lines and normal breast tissues using semiquantitative RT‐PCR." (PMID 28503860, 2017). "The aim of this study was to investigate the effect of ADAMTS-18 on tumorigenesis in a murine 4 T1 breast cancer model." (PMID 26841794, 2016). "The current data suggest that the murine 4 T1 breast tumor cell per se has weakly endogenous ADAMTS-18 expression, and ADAMTS-18 in the host mouse exerts little effect on breast tumor progression in murine 4 T1 breast cancer model." (PMID 26841794, 2016). "RT-PCR analysis showed syngeneic mammary tumor cell line 4 T1 per se has weakly endogenous ADAMTS-18 expression." (PMID 26841794, 2016). "In the HER2 transgenic spontaneous mammary tumor mouse model, we found a similar conclusion that ADAMTS18 deletion leads to the enhancement of integrin-mediated PI3K/AKT, ERK, and JNK signal activity, which increases the risk of mammary hyperplasia and breast cancer occurrence and metastasis." (PMID 38482210, 2024). "Furthermore, ectopic expression of ADAMTS18 inhibits migration and invasion of breast cancer cells via AKT and NF-κB signaling pathway, and prevents experimental lung metastasis of breast cancer." (PMID 38287441, 2024). "Whether pregnancy promotes ADAMTS18 secretion and thus affects the development of breast cancer remains to be clarified in future studies." (PMID 38287441, 2024). "In addition, the mammary tumor-bearing Her2t/w/Adamts18−/− mice exhibited significant lung metastases when compared with Her2t/w/Adamts18+/+ mice (-/- vs. + / + : 9 of 32, ~ 28% vs. 0 of 36, 0%; P = 0.0022)." (PMID 38287441, 2024). "Due to halve Her2 expression and with FVB-C57BL/6 mixed background, both Her2t/w/Adamts18−/− mice (10 of 32, ~ 31%) and Her2t/w/Adamts18+/+ mice (2 of 36, ~ 5.6%) showed significantly lower incidence of spontaneous mammary tumors when compared with Her2t/t mice (12 of 12, 100%) (P < 0.001)." (PMID 38287441, 2024). "Collectively, the 10 mammary tumor-bearing Her2t/w/Adamts18−/− mice were all accompanied by metastases, while the 2 Her2t/w/Adamts18+/+ mice exhibited only primary mammary tumors, suggesting that ADAMTS18 deficiency increases the risk of HER2-positive spontaneous mammary metastasis." (PMID 38287441, 2024). "Moreover, through analyzing the online Oncomine database, ADAMTS18 was significantly downregulated in breast cancer tissues, compared with normal breast tissues." (PMID 28503860, 2017). "ADAMTS18 methylation was observed in 34 out of 48 (70.8%) primary tumors, but not in normal breast tissues, indicating methylation‐mediated ADAMTS18 inactivation in breast cancer." (PMID 28503860, 2017). "Nude mouse model further confirmed that ADAMTS18 suppressed breast cancer metastasis in vivo." (PMID 28503860, 2017). "ADAMTS18 suppressed tumor metastasis of breast cancer in vivo." (PMID 28503860, 2017). "Here, we found that ADAMTS18 was silenced or downregulated in breast cancer cell lines." (PMID 28503860, 2017).
breast carcinoma (continued). "Demethylation treatments could restore ADAMTS18 expression in breast cancer cells, indicating that promoter methylation directly mediates its silencing." (PMID 28503860, 2017). "Thus, we cannot rule out that other signaling pathways (e.g., VEGF or TGFβ signaling pathway), may also be involved in ADAMTS18-mediated mammary tumor progression." (PMID 38287441, 2024). "Since almost all Her2t/t mice develop mammary tumor and metastasis in a relatively short period of time, it is difficult to detect differences in the incidence of mammary tumor and metastasis between Adamts18 gene knockout (Adamts18−/−) mice and the wildtype control (Adamts18+/+) mice." (PMID 38287441, 2024). "However, previous study 8 presented that ADAMTS18 methylation in breast carcinoma was 24% (5/21)." (PMID 28503860, 2017). "We next examined whether promoter methylation leads to ADAMTS18 suppression in breast cancer." (PMID 28503860, 2017). "Further mechanistic studies showed that ADAMTS18 suppressed epithelial‐mesenchymal transition (EMT), further inhibited migration and invasion of breast cancer cells." (PMID 28503860, 2017). "ADAMTS18 acts as an antagonist of AKT and NF‐κB signaling, further suppressing EMT and metastasis of breast cancer cells." (PMID 28503860, 2017). "(II) ADAMTS18 expression is reduced in primary breast cancer tissues compared to their adjacent non-cancerous tissues, largely due to promoter methylation." (PMID 38287441, 2024). "Colony formation and CCK8 assays showed that overexpression of ADAMTS18 had no detectable effect on the proliferation of breast cancer MB231 cells (P > 0.05)." (PMID 28503860, 2017). "ADAMTS18 is methylated in 70.8% of primary breast cancers, but not in normal breast tissues, indicating tumor‐specific methylation." (PMID 28503860, 2017). "There was no methylation detected in SK‐BR‐3 and YCC‐B3 breast cancer cell lines with silenced ADAMTS18, suggesting that other mechanisms like histone modifications mediated ADAMTS18 silencing." (PMID 28503860, 2017). "We did not confirm that ADAMTS-18 in the host tissues is relevant for breast tumor progress in a murine 4 T1 breast cancer model." (PMID 26841794, 2016). "In addition, ADAMTS18 in invasive ductal carcinoma (IDC) of the breast is correlated not only with tumor histological grade but also with estrogen receptor (ER), progesterone receptor (PR), and Ki67, which are markers of breast cancer." (PMID 38482210, 2024). "However, there is currently no in vivo evidence from the mouse model of spontaneous mammary cancer showing the effect of ADAMTS18 on mammary tumorigenesis and metastasis through its essential ECM regulatory function." (PMID 38287441, 2024).
Microcornea (5 papers, 2016 to 2025). A congenital abnormality of the cornea in which the cornea and the anterior segment of the eye are smaller than normal. "ADAMTS18 in human disease has been associated with microcornea, ectopia lentis, and cone rod dystrophy." (PMID 30588515, 2018). "In humans, ADAMTS18 mutations are associated with pleomorphic ocular manifestations, including microcornea, ectopic pupils, childhood cataract, night blindness, ectopia lentis, rhegmatogenous retinal detachment, and cone-rod dystrophy." (PMID 27638769, 2016). "ADAMTS18 has a listed OMIM phenotype (microcornea, myopic chorioretinal atrophy, and telecanthus, MMCAT) based on a previous study in which we reported several families with different homozygous variants; however, our finding has not been confirmed by follow up studies." (PMID 33456446, 2020). "The phenotype of the patients included bilateral Axenfeld–Rieger Syndrome (ARS), which has not been previously reported in ADAMTS18-related eye disorders, as well as microcornea, high myopia, macular changes, taurodontism and craniofacial anomalies." (PMID 41155148, 2025).
myopia (5 papers, 2018 to 2025). "ADAMTS18 mutations were reported in patients with Knobloch syndrome, a disease characterized by myopia and retinal degradation, however, this association is now unclear." (PMID 35810168, 2022). "In addition to the novel mutations found in five known myopia genes (ADAMTS18, CSMD1, P3H2, RPGR, and SLC39A5), we also identified pathogenic variants in seven ocular disease genes (ABCA4, CEP290, HSPG2, PCDH15, SAG, SEMA4A, and USH2A) as novel candidate genes." (PMID 30245926, 2018).
breast tumor (4 papers, 2016 to 2024). "We found that ADAMTS18 was readily expressed in normal breast tissues, but frequently silenced or decreased in all nine breast tumor cell lines studied." (PMID 28503860, 2017). "MSP showed that ADAMTS18 was methylated in breast tumor cell lines with its silencing or downregulation." (PMID 28503860, 2017). "Ectopic expression of ADAMTS18 in breast tumor cells resulted in inhibition of cell migration and invasion." (PMID 28503860, 2017). "ADAMTS18 expression in primary breast tumors and surgical‐margin tissues was further examined by qRT‐PCR." (PMID 28503860, 2017). "To further evaluate ADAMTS18 promoter methylation in primary breast tumors, we examined ADAMTS18 methylation in 48 primary breast tumor samples and eight normal breast tissue samples." (PMID 28503860, 2017). "It has been shown that ADAMTS-18 gene was inactivation in many carcinomas especially breast tumors and, therefore, is regarded as a novel functional tumor suppressor." (PMID 26841794, 2016). "Moreover, in samples of HER2 + tumors with distant metastases that recurred after trastuzumab treatment, ADAMTS18 expression levels were significantly lower than those in treatment-naive HER2 + primary breast tumors." (PMID 38287441, 2024). "RT‐PCR and western blot confirmed ADAMTS18 expression in ADAMTS18‐transfected breast tumor cells." (PMID 28503860, 2017). "ADAMTS18 was reduced in primary breast tumor tissues as compared with their adjacent noncancer tissues." (PMID 28503860, 2017).
Clear Cell Renal Cell Carcinoma (3 papers, 2015 to 2024). "For example, in clear renal cell carcinoma, hypermethylation of the tumour suppressor gene ADAMTS18 facilitates the proliferation, migration and invasion of tumour cells." (PMID 36811277, 2023). "Therefore, ADAMTS18 could play a tumor-suppressive role in renal clear cell carcinoma by inhibiting autophagy." (PMID 38482210, 2024). "ADAMTS18, located at 16q23.1, has been reported to be a critical TSG in multiple primary tumors; however, this has not yet been verified in clear cell renal cell carcinoma (ccRCC)." (PMID 25569086, 2015).